STAT3 (signal transducer and activator of transcription 3)
Diseases named in the same sentence as STAT3 in open-access papers (continued):
Sharing a sentence is not in itself a finding about the gene and the disease.
tumor (continued). "Key evidence has emerged demonstrating that the dual role of STAT3 depends on the tumor profile and associated mutational changes." (PMID 38339245, 2024). "The effectiveness of BP1003 is likely due to its ability to decrease STAT3 levels, which leads to decreased expression of its downstream targets, such as vimentin and Bcl-2, which have both been associated with tumor aggression and poor prognosis." (PMID 39200368, 2024). "Immune-phenotyping of Pten-deficient prostates revealed high accumulation of tumor-infiltrating leukocytes, particularly innate immune cells, neutrophils and macrophages as well as high levels of STAT3 activation and IL-1β production." (PMID 38811984, 2024). "Substantial evidence has emerged linking PDIA3 to the promotion of M2-polarization in tumor-associated macrophages and the enhancement of tissue protease secretion, mediated by the STAT3/PD-1 signaling cascade." (PMID 38761176, 2024). "ALKBH5 and tumor-associated macrophage-secreted IL-6 showed a synergistic effect to activate the JAK2/p-STAT3 pathway in cancer cells." (PMID 38872221, 2024). "In inflammation-related lung cancer, CHI3L1 is a downstream product of the inflammation-associated transcription gene STAT3, which is substantially expressed before tumor formation." (PMID 39068486, 2024). "CRISPR/Cas9-mediated STAT3 knockout was employed to evaluate the anti-tumor effects of PTPRO in STAT3-deficient cells." (PMID 38182570, 2024). "The signal transducer and activator of transcription 3 (STAT3) pathway is intimately linked to the tumor microenvironment, tumor growth, and metastasis." (PMID 39346560, 2024). "As a result, reduction of CHI3L1 levels in the primary tumor upon chitin treatment would be intricately linked to reduced Stat3 phosphorylation." (PMID 38605414, 2024). "Conversely, STAT3, found to be overexpressed in a spectrum of tumor cells, is linked to tumorigenesis, progression, and malignancy, making it a promising target for tumor radiosensitization." (PMID 38967145, 2024). "STAT3, originally identified as an acute phase response factor to IL‐6, has been well demonstrated to be associated more frequently than other STATs with tumour formation." (PMID 39099000, 2024). "IL-10-mediated drug resistance is associated with the upregulation of STAT3 signaling and antiapoptotic protein Bcl-2 in tumor cells." (PMID 39003350, 2024). "Numerous investigations have demonstrated that Stat3 inhibition increases the effectiveness of chemotherapeutic drugs in OSCC and that Stat3 hyperactivation is linked to tumor growth and treatment resistance." (PMID 39272862, 2024). "The DDX58 gene encoding RIG-I inhibits tumor cell growth, migration, and invasion through the STAT3/cysteine γ-cleaving enzyme (CSE) signaling pathway." (PMID 39867908, 2024). "One study showed that increased S1PR1 in CD4+ T-cells promotes STAT3 activation and JAK/STAT3-dependent Treg tumor migration, while ablation of STAT3 in T-cells reduces tumor-associated Treg accumulation and tumor migration." (PMID 38542328, 2024). "This facilitation takes a route through the delicate orchestration of the STAT3/PD-1 signaling confluence, contributing to a heightened state of M2 polarization in tumor-associated macrophages as well as a surge in the liberation of tissue proteases." (PMID 38761176, 2024). "Continuous activation of STAT3 by IL-6 signaling is linked to aggressive tumor behavior and poor patient prognosis in CRC." (PMID 39408697, 2024). "Inhibition of tumor growth by KIR-ESS peptide was associated to its efficacy in reducing phosphorylation of STAT3 within tumor where keratinocytes are responsible for maintaining tumor growth." (PMID 38975347, 2024). "Mechanistically, GSCs-derived IFITM3 causes activation of Jak2/STAT3 signaling and leads to robust secretion of bFGF into tumor environment, which eventually results in enhanced angiogenesis." (PMID 38218875, 2024).
tumor (continued). "Elevated expression profiles of STAT3 or p-STAT3 Tyr705 are commonly associated with higher clinical stage, higher tumor grade, lymph node metastasis, depth of invasion, chemoresistance and worse overall survival rate or disease-free survival rate." (PMID 38245798, 2024). "STAT3 is an oncogenic transcription factor with potent immunosuppressive functions, and activation of the IL-6/gp130/STAT3 pathway is associated with tumor progression and M2-polarized TAMs with pro-tumoral effects." (PMID 37553327, 2023). "By stimulation of STAT3, M2 macrophages, which in a tumor are named tumor-associated macrophages, support population, invasion, and drug resistance of CSCs." (PMID 37328876, 2023). "IL11/STAT3 signaling effects downstream cyclin, which reflected in this study is that Ki67+ tumor cells were reduced both in IL11-deficient and IL11 mutein-treated tumors." (PMID 37365574, 2023). "For instance, IL-6, by activating the STAT3 signaling pathway, fosters M2 macrophage differentiation, which in turn is associated with activities that promote tumor growth and progression." (PMID 38035068, 2023). "IL-6 is reportedly secreted by tumor cells and cancer-associated fibroblasts in response to platinum treatment, enhancing chemoresistance via STAT3-mediated enrichment of cancer stem cells." (PMID 37124547, 2023). "CC wasting in mice with STK11/LKB1-variant tumors was associated with significant alterations in tumor microenvironment immune cell repertoire, concomitant amplification of local and systemic pro-inflammatory cytokines, and host adipose STAT3 activation." (PMID 37092555, 2023). "The application of curcumin/STAT3 siRNA-loaded liposomes caused significant tumor growth inhibition in contrast with the treatment using control liposomes and naked STAT3 siRNA in the melanoma cancer model." (PMID 38067351, 2023). "We observed that non-responders showed elevated levels of proinflammatory mediators, such as IL-1RA, IL-6, IL-8 and to lesser extent IL-10, which are associated with STAT3 activation and tumor immunosuppression." (PMID 38259453, 2023). "Aberrant activation of the STAT3 signalling pathway has been linked to tumour cell proliferation and tumourigenesis." (PMID 36825563, 2023). "The role of STAT3 in inducing PD-L1, extorting prooncogenic functions, has been demonstrated in several tumor models characterized by the JAK2V617F variant." (PMID 36672229, 2023). "This study has demonstrated a significant association between high expression of STAT3 within the tumour‐associated stroma and reduced CSS in patients with TNBC." (PMID 37199043, 2023). "In patients with GC, IL-10 secreted by tumor-associated macrophages regulates the proliferation and invasion of GC cells via c-mesenchymal epithelial transition protein/STAT3 signaling." (PMID 37946227, 2023). "Tumor cells with dysfunctional STAT3-S727A mutation in mitochondria have decreased GSH expression, increased Mito-ROS production, and Mito dysfunction that increased tumor cell apoptosis." (PMID 37526084, 2023). "Nuclear TRIM59 then promotes ubiquitination and degradation of the tumor-suppressive histone variant macroH2A1, causing STAT3 activation and tumorigenicity." (PMID 37993880, 2023). "Studies have revealed that HCC-derived exosomes can modulate tumor immune evasion by up-regulating PD-L1 expression in tumor-associated macrophages through the STAT3 signaling pathway." (PMID 38254641, 2023). "STAT3 is associated with tumor cell proliferation, invasion and immunosuppression, and JAK-STAT3 signaling promotes cancer through inflammation." (PMID 37057285, 2023). "MiR-648 is predicted to regulate 3 feature genes (DDIT3, CXCL2, and STAT3) and has been linked to inhibiting tumor development and overcoming chemotherapy resistance." (PMID 37422588, 2023). "STAT3 induces VEGF expression in the association of hypoxia-inducible factor 1-alpha (HIF1A) to promote tumor angiogenesis." (PMID 37860678, 2023).
tumor (continued). "Taken together, these data show that STAT3–/– T cells preserve strong GVL activity against not only BCL1 tumor cells but also non–GVL-susceptible ALL tumor cells, while inducing only mild and transient or reversible acute GVHD." (PMID 37526084, 2023). "Studies have demonstrated a critical role of STAT3 signaling in the persistence of cancer stem cells (CSCs), which is a primary cause of tumor relapse and metastasis." (PMID 37686148, 2023). "Firstly, STAT3/Foxp3 axis was associated with tumor progress in EC and enhanced Tregs infiltration, as well as the potential treatment option for Tregs inhibition." (PMID 36226375, 2023). "To elucidate the molecular mechanisms underlying the synergistic anti-tumor effect of the alectinib and DNA-demethylating agent combination therapy, we first confirmed the status of DNA methylation and STAT3 phosphorylation in ALCL cells." (PMID 37894456, 2023). "Apoptotic cell death can be triggered by inhibition of the mTOR/STAT3 signaling pathways that are closely linked with tumor progression." (PMID 37446140, 2023). "Previous studies have demonstrated that EMT activation, angiogenesis, and IL-6/JAK/STAT3 pathways increase the risk of tumor invasion, metastasis, and drug resistance." (PMID 37874419, 2023). "STAT3 is a pro-inflammatory and carcinogenic transcription factor linked to tumor occurrence, inflammation, and immunosuppression." (PMID 36672337, 2023). "Conversely, when STAT3 inhibitors were applied in clinical settings for targeting tumor-associated myeloid cells, the studies were disrupted by the side effects." (PMID 36739406, 2023). "In terms of this, STAT3 and Foxp3 interaction site was exist in the promoter of tumor induced Tregs and associated with several tumors progression." (PMID 36226375, 2023). "A study reported that the constitutive activation of STAT3 promotes the accumulation of M2 tumor-associated macrophages (TAMs), which play a key role in suppressing the antitumor mechanism and inducing tolerance to tumor antigens." (PMID 38201528, 2023). "In particular, high STAT3 expression within the tumour‐associated stroma was associated with significantly reduced CSS (HR = 2.202, 95% CI: 1.148–4.224, log rank p = 0.018)." (PMID 37199043, 2023). "Recently, research has suggested that IL-17A-mediated neovascularization is inextricably linked with the IL-6/STAT3 pathway in animal tumor models." (PMID 36873773, 2023). "Seyedi and her colleagues showed that downregulation of STAT3 resulted in the switching of M2 to M1 in the tumor microenvironment, in turn causing inhibition of tumor progression." (PMID 36662090, 2023). "STAT-3 associates with V-ATPase in a coiled manner and regulates the activity of the V-ATPase which is important for the maintenance of the tumor microenvironment." (PMID 36601166, 2023). "Using genetically engineered mouse models (GEMMs), we show that genetic inactivation of Stat3 in Ptenpc−/− mice shortens survival, whereas constitutive Stat3 activation causes tumor regression and prolongs survival beyond PTEN deficiency." (PMID 37573301, 2023). "In an animal model, the functional inactivation of STAT3 is associated with reduced tumour growth, if neoplastic cells are injected in nude mice." (PMID 37108193, 2023). "Elevated expression of IL-6 leads to activation of JAK-STAT signaling, a cornerstone to cancer progression in particular linked to STAT3 activation, both through tumor growth and metastasis as well as modulation of immune surveillance." (PMID 37745296, 2023). "They examined the expression levels of miRNA520c and STAT3 and observed that lower levels of miRNA-520c were associated with higher tumor malignancy and increased invasiveness into adjacent tissues." (PMID 37958993, 2023). "Activation of STAT3 in tumor-associated endothelial cells, TAMs, and cancer cells, induces their ability to express basic fibroblast growth factor (bFGF) and VEGF, promoting rapid vascularization." (PMID 36835413, 2023).
tumor (continued). "STAT3 often interacts with other signaling pathways, such as NF-ĸB, commonly associated with lung inflammation and confers robustness in tumor progression." (PMID 36986550, 2023). "STAT1 is considered as a tumor suppressor, linked with the M1 phenotype, whereas STAT3 is thought as a tumor promoter." (PMID 38098217, 2023). "In turn, educated mesenchymal stem cells release IL-6 associated with STAT3 activation and tumor progression with the formation of lung metastatic foci." (PMID 37329384, 2023). "Upon tyrosine phosphorylation by receptor-associated tyrosine kinases, STAT3 translocates to the nucleus and activates the expression of downstream genes to regulate tumor cell growth, proliferation, differentiation, and metastasis." (PMID 37057281, 2023). "considered phosphorylated STAT3 the key factor inducing MDSCs to differentiate into tumor‐associated macrophages (TAMs), reporting that tumor‐infiltrating MDSCs had a lower phosphorylated STAT3 level to retain their immature state." (PMID 37547175, 2023). "Overexpression of STAT3 regulates tumor progression and is associated with poor prognosis in various malignancies." (PMID 37511453, 2023). "Deleterious SNPs of the STAT3 gene are capable of regulating the expression, stimulation, and predisposition in inflammatory and neoplastic diseases." (PMID 37860678, 2023). "Constitutive activation of the STAT3 pathway in cancer has previously been implicated in promoting tumour proliferation, invasion, and metastasis." (PMID 37433987, 2023). "The PI3K/Akt, Wnt/catenin, and Src pathways are all implicated, as are interleukin-induced STAT3 activation, epigenetic modulators, redox states, and the tumor microenvironment." (PMID 37453969, 2023). "In this study, CPA-7, an inhibitor of Stat3 dimerization, and STAT3 siRNA were used efficiently to reverse the immune profile of TAMs and cause tumor growth inhibition in the GL261 GBM mouse model." (PMID 37190507, 2023). "Blockade of STAT3 in tumor-associated myeloid cells increases the turning IMCs to DCs and TAMs, and decreases the recruitment of MDSCs to eliminate immunosuppressive function." (PMID 37217620, 2023). "In a mouse model, STAT3-deficient NK cells enhance tumor immune surveillance and increase DNAM-1 and the lytic enzymes perforin and granzyme B secretion." (PMID 36911202, 2023). "Together with immunosuppressive cytokines secreted by tumor‐associated macrophages, hypoxia activated the STAT3 pathway, triggering hypoxia‐induced immunosuppression in subtype C3." (PMID 36688633, 2023). "Its deficiency diminishes tumor size, suppresses carcinogenesis/proliferation, spheroid growth, and signal transducer and activator of transcription 3 (STAT3) phosphorylation." (PMID 37834160, 2023). "STAT3 signaling and macrophage-produced IL-6 that promotes tumor cell proliferation are linked to TAM-mediated resistance to carboplatin." (PMID 37211559, 2023). "Tumor cells are able to stimulate miR-214 expression in the stroma counterparts which is linked to IL-6 production and IL-6/STAT3 signaling." (PMID 36639824, 2023). "Tumor-associated macrophages (TAMs) promote tumor progression in liver tissue microenvironments by releasing IL-6, which, in turn, activates the IL-6/STAT3 signaling pathway in nearby HCC stem cells." (PMID 37892997, 2023). "Tumor-derived exosomes associated with Hsp72 trigger Stat3 phosphorylation in MDSCs in a TLR2/MyD88-dependent manner via autocrine IL-6 signaling, thus enhancing the immunosuppressive function of MDSCs84." (PMID 37553810, 2023). "A chemical-induced animal model study revealed that orally administered VSL#3 probiotic cocktail meliorated colitis-associated tumor development through the reduction of STAT-3 expression." (PMID 37265504, 2023). "IL-17, for example, is linked to NSCLC tumor progression via STAT3/NF-κB/Notch1 signaling in Th17 cells, and inhibition of the pathway was found to slow metastases." (PMID 35881197, 2023).
tumor (continued). "It was observed that the expression of pSTAT3 was suppressed in the siRNA and inhibitor groups (activators of CMA, including 6-aminonicotinamide and nutrient starvation), thus suggesting a role for the association of MLLT11 with STAT3 in tumor growth." (PMID 38075552, 2023). "The OOE treatment modified the activation of ERK, Src, and STAT3 signaling pathways, thereby regulating the expression of STAT3-downstream genes that are associated with tumor formation." (PMID 37958889, 2023). "Signal transducer and activator of transcription 3 (STAT3) has been reported to be associated with tumor progression as a member of the STAT protein family." (PMID 38067413, 2023). "In conclusion, these findings shed crucial light on the dynamic interplay between LIF secretion and STAT3 activation, providing valuable insights into the regulatory mechanisms underlying stemness in tumor-derived cells." (PMID 38137514, 2023). "Increased levels of IL-6 in the tumour microenvironment and/or mutations of loss-of-function mutations affecting STAT3 negative regulators result in STAT3 hyperactivation in tumour cells." (PMID 37753372, 2023). "Cytokines activate or inhibit STAT3 activity in hematopoietic progenitors to maintain moderate hematopoietic levels; however, hyperactivation or mutation of STAT3 can lead to tumor development." (PMID 37833363, 2023). "Elevated serum SCCA and high tumor p-STAT3 are associated with CD11b expression and poor cancer-specific survival after CRT." (PMID 37279067, 2023). "Previous work has shown that the tumor suppressive function of STAT3 is closely linked to PTEN, a tumor suppressor protein that inhibits PI3K/AKT signaling." (PMID 37573301, 2023). "Kaplan–Meier survival analysis revealed high cytoplasmic expression of STAT3 within the tumour epithelium was associated with reduced outcome in the full cohort (HR = 1.502, 95% CI: 1.066–2.118, log rank p = 0.020)." (PMID 37199043, 2023). "There are numerous reports on STAT3 in BC as an early-stage tumor diagnostic marker and it is known to induce BC malignancy." (PMID 38213901, 2023). "STAT3 is the most studied gene and is closely associated with tumor growth and immune escape in most tumors, while STAT5 is mainly in hematologic tumors." (PMID 38098217, 2023). "p-STAT3 can promote tumor progression by increasing transcription of genes associated with stemness and epithelial to mesenchymal transition (EMT)." (PMID 36902166, 2023). "The expression of STAT3 in cancer-associated fibroblasts promotes the recruitment of myeloid-derived suppressor cells (MDSCs) in to the tumor by the production of C-C motif chemokine ligand 2 (CCL2) to create an immunosuppressive TME." (PMID 38273841, 2023). "In both tumor entities, STAT3 expression is associated with tumor progression and mediates immune suppression." (PMID 37047709, 2023). "STAT3 is considered a target for anticancer therapy since it is associated with tumor initiation and progression." (PMID 37958443, 2023). "Activation of STAT3 in endothelial cells has also been linked to an increase in cell adhesion molecules and tumor cell invasion." (PMID 37440925, 2023). "Effects of cancer cell-extrinsic STAT3 deficiency on anti-tumor immunity have initially been reported in an inducible STAT3 knockout mouse model (Stat3fl/fl Mx1-Cre mice)." (PMID 35865518, 2022). "For example, tumor-associated MSCs are reported to modulate the expression of cysteinase via the IL-10/STAT3 signaling pathway, thereby inhibiting the production of cysteine by DCs and suppressing the proliferation of naïve T cells." (PMID 36439438, 2022). "The expression level of multiple genes associated with tumor growth, such as STAT3, PDGFA, PLD2, and PIK3R2, showed a significant decrease." (PMID 35291563, 2022).